PDGFA (platelet derived growth factor subunit A)
Diseases named in the same sentence as PDGFA in open-access papers (continued):
Sharing a sentence is not in itself a finding about the gene and the disease.
Insulin resistance (3 papers, 2020 to 2025). Increased resistance towards insulin, that is, diminished effectiveness of insulin in reducing blood glucose levels. "Increased liver methylation expression in PDGFA is associated with hyperinsulinemia and insulin resistance, even after adjusting for BMI and other factors." (PMID 38460073, 2024). "Both PDGFA overexpression and hypomethylation at a CpG site in PDGFA are associated with an increased risk of developing insulin resistance, type 2 diabetes, and steatohepatitis." (PMID 32372975, 2020).
lung fibrosis (3 papers, 2022 to 2025). "Recent studies have found that in bleomycin-induced lung fibrosis, the early production of TGF-β and platelet derived growth factor subunit A (PDGFA) by senescent AECII may directly promote fibroblast activation and collagen production, which in turn promotes fibrosis." (PMID 36457712, 2022). "Overall, our results point to a down-expression of PDGFA and TGFB in blood cells with the presence of lung fibrosis, as opposed to the overexpression reported at the tissue level." (PMID 41226758, 2025).
malignant glioma (3 papers, 2004 to 2024). A grade III or grade IV glioma arising from the central nervous system. "Our analysis identified PDGFRA and PDGFA—both of which are findings from our investigation—as key genes significantly enriched in pathways that are critical for malignant glioma processes." (PMID 39606019, 2024).
medulloblastoma (3 papers, 2010 to 2021). A malignant, invasive embryonal neoplasm arising from the cerebellum. "Overall, inhibition PDGFA, CXCR4, BOC, MET, and NGFR have all shown therapeutic promise in SHH-subgroup medulloblastoma." (PMID 34667228, 2021).
Nephroblastoma (3 papers, 2012 to 2021). An embryonal neoplasm characterized by the presence of epithelial, mesenchymal, and blastema components. "PDGFA overexpression was associated with higher T stage in papillary thyroid cancer and nephroblastoma, implying that PDGFA probably played an important role in the invasion of cancer cells." (PMID 34011067, 2021).
oligoastrocytoma (3 papers, 2011 to 2024). A WHO grade II tumor composed of a conspicuous mixture of two distinct neoplastic cell types morphologically resembling the tumor cells in oligodendroglioma and diffuse astrocytoma. "Yet, over the course of six months, these cells, even after two passages through mice, did not expand in suspension culture in serum free medium supplemented with FGF, and EGF and/or PDGFA, as has been previously reported for other oligodendroglioma and oligoastrocytoma cell populations." (PMID 23527265, 2013).
astrocytomas (2 papers, 2017 to 2019).
multiple myeloma (2 papers, 2014 to 2024). "It has recently been demonstrated that the forced expression of HOXB7 in multiple myeloma induces the up-regulation of VEGFA, FGF2, MMP2 and PDGFA, and the down-regulation of thrombospondin 2, a profile largely shared by RC." (PMID 25115389, 2014).
oral squamous cell carcinoma (2 papers, 2021 to 2024). "Targeting PDGFA may inhibit metastasis and invasion of oral squamous cell carcinoma." (PMID 39012409, 2024).
sarcoma (2 papers, 2019 to 2021). A usually aggressive malignant neoplasm of the soft tissue or bone. "The results presented here show that the overexpression of PDGFA might correlate with tumor aggressiveness in sarcoma: overexpression of PDGFA, a PDGFRα-specific ligand, was an independent adverse prognostic factor." (PMID 33524869, 2021). "In the non-GIST sarcoma cohort, histological subtype, location, grade, tumor size, PDGFA and PDGFD expression levels were introduced in the multivariate model." (PMID 33524869, 2021).
thyroid cancer (2 papers, 2009 to 2019). "Recently, PDGFA and PDGFRA were reported up-regulated in thyroid carcinoma cell lines and autocrine activation of PDGFRA was suggested to play a crucial role in the carcinogenesis of thyroid cells." (PMID 19968886, 2009). "In addition, PDGFA and PDGFRA were recently reported overexpressed in two thyroid carcinoma cell lines, one derived from PTC, the other from FTC." (PMID 19968886, 2009).
acute myeloid leukemia (1 paper, 2022). Acute myeloid leukemia (AML) is a group of neoplasms arising from precursor cells committed to the myeloid cell-line differentiation. "The lncRNA H22954 inhibits angiogenesis in acute myeloid leukemia by downregulating PDGFA expression." (PMID 35958561, 2022).
adrenocortical adenomas (1 paper, 2018). "Moreover, PDGFD is highly expressed in human adrenal gland, unlike PDGFA, PDGFB, and PDGFC, and the expression of PDGFD correlates negatively with cortisol secretion in adrenocortical adenomas." (PMID 29551627, 2018).
adult T-cell leukemia/lymphoma (1 paper, 2024). A peripheral (mature) T-cell neoplasm linked to the human T-cell leukemia virus type 1 (HTLV-1), adult T-cell leukemia/lymphoma is endemic in several regions of the world, in particular Japan, the Caribbean, and parts of Central Africa. "In contrast, in adult T-cell leukemia/lymphoma (ATLL), CAFs promote CD4+ T cell proliferation via FGF7-FGF1 and PDGFA-PDGFRA/B signaling." (PMID 39555055, 2024).
AIDS (1 paper, 2018). A syndrome resulting from the acquired deficiency of cellular immunity caused by the human immunodeficiency virus (HIV). "We found that KSHV-LANA staining appears in areas corresponding to phosphorylated PDGFRA, as well as, diffuse PDGFA and PDGFB expression in mECK36 tumors and in AIDS-KS lesions." (PMID 29985958, 2018). "The existence of a KSHV-induced, ligand-mediated mechanism for PDGFRA activation is supported by immunohistochemistry staining of mECK36 and AIDS-KS lesions showing that the areas staining for both KSHV-LANA and phospho-PDGFRA correspond with the detection of PDGFRA ligands PDGFA and PDGFB." (PMID 29985958, 2018).
allergic disease (1 paper, 2023). An immune response that occurs following re-exposure to an innocuous antigen, and that requires the presence of existing antibodies against that antigen. "Some calcium signaling pathway-related genes, such as ERBB2, PDE1B, PDGFA, TPCN1, and MCU, have been reported to participate in the development of allergic diseases." (PMID 37328853, 2023).
cerebrovascular diseases (1 paper, 2024). "As a specific receptor of PDGFA, PDGFRα is involved in a variety of pathways related to cardiovascular and cerebrovascular diseases and is of great significance for angiogenesis, inflammatory response, cell survival and apoptosis, cell proliferation and migration." (PMID 38195688, 2024). "There were 6 genes related to cardiovascular and cerebrovascular diseases, which were Fgd3, Myoz3, AC095693.1, Adamts3, PDGFA and PDGFRα." (PMID 38195688, 2024). "Genes related to cardiovascular and cerebrovascular diseases annotated by the PI3K-Akt signaling pathway included Fgf12, Fgfr1, PDGFA, and PDGFRα." (PMID 38195688, 2024).
Depression (1 paper, 2012). "The mRNA expression profile associated with Any Depression (AD) included four genes, three of them (PDGFA, PF4, and TGF-β1) were down-regulated (P-values: <0.0054, <0.0123 and <0.0152; respectively), while the STAT4 gene was up-regulated (P-value <0.0396)." (PMID 23139898, 2012). "Indeed, in our study, both the presence of “Any Depression” as well as “Treatment-related Depression” resulted in significantly lower expression of PDGFA." (PMID 23139898, 2012).
Distichiasis (1 paper, 2020). Double rows of eyelashes. "Based on known function, PDGFA was considered most likely to be involved in distichiasis." (PMID 33256610, 2020).
gastric ulcer (1 paper, 2013). An ulcerated lesion in the mucosal surface of the stomach. "Neither VEGF nor PDGFA was elevated in gastric ulcer margin of the cirrhotics and non-cirrhotics in our study, which was not consistent with previous studies showing increased VEGF and PDGF expression during gastric ulcer healing both in humans and in experimental animals." (PMID 23620752, 2013).
gastrointestinal stromal tumor (1 paper, 2020). "Furthermore, the drug repurposing approach is even more applicable for STS with oncogenic mutations: gastrointestinal stromal tumors (GIST) with activating mutations in c-KIT, PDGFA and BRAF, myxoid round cell liposarcoma with activating mutation in PI3K/Akt signaling component PI3CA." (PMID 32317857, 2020).
germ cell neoplasm (1 paper, 1991). "In comparison with normal DNA, tumour DNA of a total of eight patients (seven with germ cell neoplasm and one with testicular lymphoma) showed increased dosages of KRAS2, PDGFA, EGFR, MET and PDGFB." (PMID 1829952, 1991).
ischemia (1 paper, 2016). A hypoperfusion of the BLOOD through an organ or tissue caused by a PATHOLOGIC CONSTRICTION or obstruction of its BLOOD VESSELS, or an absence of BLOOD CIRCULATION. "PDGFA is a well-characterized pro-angiogenic factor in different physiological and pathological conditions including organ development, ischemia and renal diseases." (PMID 27029061, 2016).
ischemic stroke (1 paper, 2025). A stroke disorder caused by obstruction of blood flow to the brain, due to thrombotic (local blood clot formation) or embolic (due to a blood clot or other material traveling from another site) event. "Increased expression of growth/differentiation factor-5 (GDF5) and platelet-derived growth factor subunit A (PDGFA) is observed following tDCS in a mouse model of ischemic stroke." (PMID 40438568, 2025).
laryngeal carcinoma (1 paper, 2022). Carcinoma that arises from the laryngeal epithelium. "Prognosis-related IRGs were then explored by univariate cox regression analysis and correction of clinical factors, AQP9, CXCL11, IGHV4.31, PDGFA and ZAP70 were significantly correlated to laryngeal cancer prognosis." (PMID 35477402, 2022).
lung adenoma (1 paper, 2015). A benign, well circumscribed epithelial neoplasm that arises from the bronchus or the lung parenchyma. "In this model, we have found that immature macrophage-lineage cells (IMCs) producing PDGFA, TGFβ and CC chemokines are recruited to the stroma of premalignant lung adenomas through CC chemokine receptor 1 (CCR1)-dependent mechanisms." (PMID 26183450, 2015).
mast cell tumors (1 paper, 2022). "Toceranib targets receptor tyrosine kinases, including C-KIT, VEGFR-2, PDGFa/b, and CSF-1 (colony stimulating factor–1) and is used as a first-line treatment for dogs with mast cell tumors." (PMID 36012610, 2022).
metastatic disease (1 paper, 2017). "In both situations, the HIF1-α gene moves to the cell nucleus, promoting VEGFA and PDGFa transcription, As a result many drugs targeting angiogenesis have been developed and are currently being used to treat metastatic disease." (PMID 29202733, 2017).
migraine (1 paper, 2022). "Neuropeptides directly associated with pain or migraine from significantly differentially expressed neuropeptide prohormone genes include apelin (APLN), cortistatin (CORT), IGF2, neuromedin B (NMB), neuropeptide W (NPW), PDGFA and platelet-derived growth factor, D polypeptide (PDGFD), TAC4, and VIP." (PMID 35453627, 2022).
orofacial cleft (1 paper, 2018). A disorder of facial skeleton that is characterized by cleft lip and/or cleft palate that result in feeding, speech and hearing problems caused by failures during development. "Except for “Platelet derived growth factor subunit A” (PDGFA), few of the genes in the network have previously been linked to orofacial clefts." (PMID 29535761, 2018).
ovarian serous cystadenocarcinoma (1 paper, 2018). A malignant serous cystic epithelial neoplasm arising from the ovary. "Recent studies have shown that FBXL7 expression was positively correlated with CD44, PDGFA, PDGFC, and PDGFD in ovarian serous cystadenocarcinoma." (PMID 30301218, 2018). "The results showed that FBXL7 expression was positively correlated with CD44, PDGFA, PDGFC, and PDGFD in ovarian serous cystadenocarcinoma tissues with a statistical significance (p = 0.001 or p < 0.001)." (PMID 30301218, 2018). "In addition, FBXL7 expression was positively correlated with CD44, PDGFA, PDGFC, and PDGFD in ovarian serous cystadenocarcinoma." (PMID 30301218, 2018).
phyllodes tumor (1 paper, 2023). A benign, borderline, or malignant fibroepithelial neoplasm arising from the breast and rarely the prostate gland. "Overexpression of EGFR and PDGFA is also present in malignant phyllodes tumors, which suggests the potential use of dual VEGFR/EGFR inhibitors (Vandetanib), a combination of anti-VEGFR and anti-EGFR and multikinase inhibitors (Panzopnib)." (PMID 37240386, 2023).
pituitary tumor (1 paper, 2022). A benign or malignant neoplasm affecting the pituitary gland. "The expression of PDGFA, PDGFB, TGFB1 and TGFB2 in pituitary tumor tissue was respectively 3.5 x104, 2.0 x 104, 1.3 x 105 and 6.6 x 103 copies/μg total RNA." (PMID 35600354, 2022). "Pituitary tumors also expressed significantly higher levels of angiogenesis growth factors, including VEGFA (4.2-fold), VEGFB (2.2), VEGFC (19.3), PGF (13.4), ANGPT2 (9.2), PDGFA (2.7), PDGFB (10.5) and TGFB1 (3.8) compared to normal pituitary tissue." (PMID 35600354, 2022).
renal fibrosis (1 paper, 2022). A final common manifestation of a wide variety of chronic kidney diseases characterized by glomerulosclerosis and tubulointerstitial fibrosis. "Moreover, it was associated with an elevation in renal fibrosis markers: TGF-β, PDGFA and ASMA." (PMID 35203394, 2022).
rheumatoid arthritis (1 paper, 2025). A chronic, systemic autoimmune disorder characterized by inflammation in the synovial membranes and articular surfaces. "We evaluated PDGFA, TGFB1, TGFB2, and TGFB3 role in the diagnosis of ILD associated with rheumatoid arthritis (RA), systemic sclerosis (SSc), and inflammatory myopathies (IM)." (PMID 41226758, 2025).
serous ovarian cancer (1 paper, 2020). "The prognostic value of PDGFA and ENA78 mRNA expression in serous ovarian cancer patients was evaluated using the online tool KM plotter, which evaluates the effect of 22,277 genes and their expression." (PMID 32962103, 2020).
skin melanoma (1 paper, 2021). "ANGPT2 gene expression is significantly higher (P < 0.01) in skin melanoma compared to normal skin, whereas expression of ANGPT1, PDGFA, FGF2, and VEGF‐A is not significantly different." (PMID 34102002, 2021).
small cell lung carcinoma (1 paper, 2024). Small cell lung cancer (SCLC) is a highly aggressive malignant neoplasm, accounting for 10-15% of lung cancer cases, characterized byrapid growth, and early metastasis. "Interestingly, copy number gains involving this genomic region known to harbor oncogenes such as UNCX, FAM20C, MAD1L1 and PDGFA have been reported during the immortalization process of patient-derived small cell lung cancer lines." (PMID 39737401, 2024).
triple-negative breast carcinoma (1 paper, 2020). An invasive breast carcinoma which is negative for expression of estrogen receptor (ER), progesterone receptor (PR), and human epidermal growth factor receptor 2 (HER2). "Additionally, we explored TCGA data and analyzed the correlation between C3aR1+PDGFA+ expression and the survival of triple negative breast cancer patients, we found that patients with a high level of C3aR1+PDGFA+ expression had a poorer survival rate." (PMID 31931851, 2020).
tumor (129 papers, 1991 to 2026). "We also predicted the interactions of nmTECs with vascular endothelial cells via VEGFA and VEGFE and with tumor-associated fibroblasts via PDGFA-PDGFRA." (PMID 35869073, 2022). "The stimulation of PDGFA signaling has been observed in GBMs and is associated with tumor initiation and malignant progression." (PMID 31300060, 2019). "PDGFA expression was also observed in tumour-associated endothelial cells and in basal membrane of blood vessels in approximately 12% (19 out of 160) of the cases." (PMID 19707201, 2009). "WT1 activates the PDGFA gene in desmoplastic small round-cell tumor, which contributes to the fibrosis associated with this tumor." (PMID 19737418, 2009). "After stringent quality control, we isolated 2968 fibroblasts and identified two primary fibroblast classes through unsupervised clustering: tumor-associated fibroblasts (CAF_C1_CLU, CAF_C2_MME) and tumor-associated myofibroblasts (myCAF_C1_MYH11, myCAF_C2_PDGFA)." (PMID 38720887, 2024). "In the TCGA-HNSC cohort, we found that ACTB, MAP2K1, PARVB, and PDGFA were upregulated in tumour tissues, suggesting that gene expression may be associated with tumourigenesis." (PMID 37691922, 2023). "Furthermore, IRGs associated with tumor progression, including PDGFA, ITPR3, SLPI, TICAM1, and GATA4, were identified." (PMID 36588538, 2022). "The results demonstrated that PDGFA expression remained independently associated with OS (HR, 1.536; 95% CI, 1.034–2.282; P = .034), as well as N stage (HR, 2.143; 95% CI, 1.400–3.279; P = .000) and tumor location (lower vs upper: HR, 0.488; 95% CI, 0.255–0.934; P = .030)." (PMID 34011067, 2021). "These pathway-level changes were accompanied by reduced expression of transcripts frequently associated with tumor-promoting programs, such as SERPINA1, MDM2, PDGFA, TGFBR1/2, and SPINK1." (PMID 41596590, 2026). "Investigating these classical markers in our data, we did observe a statistically significant increase of TNF (TNF‐α) in G1 tumors, FGF14 in G2 tumors, and FGF8, FGF18, and PDGFA in G3 tumor in comparison to pancreatic islet cells." (PMID 39245631, 2025). "Surprisingly, we found that ESM1 and PDGFB are expressed in the same tumor regions, while the distributions of PDGFA and PDGFC seem to be mutually exclusive with those of PDGFB and ESM1." (PMID 39773984, 2025). "We further investigated the consequence of PDGFRA regulation by autophagy using a mouse model for gliomagenesis where we observed a disruption in PDGFA-driven tumor formation when autophagy is inhibited." (PMID 38634484, 2024). "For instance, PDGFB expression has been closely linked to the development of tumor stroma in melanoma, and PDGFA facilitated recruitment of PDGFR-positive stromal fibroblasts to tumor periphery in xenograft mouse models of lung carcinoma." (PMID 38234683, 2023). "The expression level of multiple genes associated with tumor growth, such as STAT3, PDGFA, PLD2, and PIK3R2, showed a significant decrease." (PMID 35291563, 2022). "PDGFA belongs to the platelet-derived growth factor protein family, which regulates the tumor microenvironment of HNSCC through the PDGF/AKT signaling pathway." (PMID 34220923, 2021). "Tumor size and PDGFA expression levels were identified as independent adverse prognostic factors (P = 1.3 × 10−4 and P = 4.3 × 10−2, respectively) while PDGFD expression levels were a favorable prognostic factor for metastasis-free survival (P = 4.99 × 10−3)." (PMID 33524869, 2021).